ENPP7 (ectonucleotide pyrophosphatase/phosphodiesterase 7)
Description:
Choline-specific phosphodiesterase that hydrolyzes sphingomyelin releasing the ceramide and phosphocholine and therefore is involved in sphingomyelin digestion, ceramide formation, and fatty acid (FA) absorption in the gastrointestinal tract. Also has phospholipase C activity and can also cleave phosphocholine from palmitoyl lyso-phosphatidylcholine and platelet-activating factor (PAF) leading to its inactivation. Does not have nucleotide pyrophosphatase activity. May promote cholesterol absorption by affecting the levels of sphingomyelin derived from either diet or endogenous sources, in the intestinal lumen (By similarity).
Synonyms: E-NPP 7; NPP-7; Alk-SMase; NPP7
Tractability: Small molecule: a structure with a bound ligand is known; a high-quality ligand is known. Antibody: UniProt places it where antibodies can reach, with high confidence; its Gene Ontology location is reachable by antibodies, with high confidence; UniProt predicts a signal peptide or a membrane-spanning region.
Target class: Enzyme; Phosphodiesterase
Gene: Protein-coding gene on chromosome 17 (79,728,809 to 79,742,930, forward strand). Ensembl gene ENSG00000182156.
Subcellular location: Cell membrane
Pathways (Reactome):
Metabolism: Glycosphingolipid catabolism
Gene Ontology:
Molecular function: phosphoric diester hydrolase activity; protein binding; sphingomyelin phosphodiesterase activity; zinc ion binding
Biological process: negative regulation of cell population proliferation; negative regulation of DNA replication; sphingomyelin metabolic process; fatty acid homeostasis; glycosphingolipid catabolic process; lipid digestion; positive regulation of ceramide biosynthetic process; positive regulation of intestinal cholesterol absorption; positive regulation of sphingomyelin catabolic process; regulation of intestinal lipid absorption
Cellular component: Golgi apparatus; microvillus; plasma membrane; membrane
Genetic constraint (gnomAD): Loss-of-function variants: 39 observed, 34.63 expected, observed/expected ratio (o/e) 1.13, 90% interval 0.87 to 1.47. The upper end of that interval is the gene's LOEUF score, 1.47, which puts it in group 6 of 6, group 1 being the genes least tolerant of losing a copy. Missense variants: 592 observed, 658.1 expected, observed/expected ratio (o/e) 0.9, 90% interval 0.84 to 0.96. Synonymous variants: 243 observed, 278.38 expected, observed/expected ratio (o/e) 0.87, 90% interval 0.79 to 0.97.
Homologues: Orthologues: chimpanzee ENPP7 (98% identical), macaque ENPP7 (95% identical), pig ENPP7 (80% identical), dog ENPP7 (79% identical), rat Enpp7 (78% identical), mouse Enpp7 (76% identical), rabbit ENPP7 (62% identical), tropical clawed frog enpp7 (58% identical), zebrafish enpp7.1 (51% identical), zebrafish enpp7.2 (51% identical), Caenorhabditis elegans enpp-1 (24% identical), Caenorhabditis elegans C27A7.3 (23% identical). Paralogues in human: ENPP5 (32% identical), ENPP1 (30% identical), ENPP3 (28% identical), ENPP6 (28% identical), ENPP4 (28% identical), ENPP2 (27% identical).
Diseases named in the same sentence as ENPP7 in open-access papers:
ENPP7 is named in the same sentence as 30 diseases in open-access papers, as found by Europe PMC text mining. Sharing a sentence is not in itself a finding about the gene and the disease. The quoted sentences say what the papers report.
colon carcinoma (11 papers, 2007 to 2025). "In colon cancer, intestinal ENPP7 is localized in the enterocytes, which may have antiproliferation effects on tumor cells." (PMID 36986671, 2023). "Alkaline SMase (Alk-SMase or ENPP7), which is found in intestinal mucosa, bile, and liver, was shown to reduce colon cancer progression in a mice model." (PMID 35565311, 2022).
colitis (6 papers, 2014 to 2026). Inflammation of the colon. "RESULTS: ENPP7 deficiency significantly aggravated DSS-induced colitis, as evidenced by greater body weight loss, higher DAI scores, and shorter colon length." (PMID 41981505, 2026). "This study aimed to investigate the role of ENPP7 in dextran sulfate sodium (DSS)-induced colitis, with a particular focus on oxidative stress and FOXO1-related signaling pathways." (PMID 41981505, 2026). "METHODS: ENPP7 knockout (KO) and wild-type (WT) mice were used to establish a DSS-induced colitis model." (PMID 41981505, 2026).
diabetes (3 papers, 2021 to 2023). "Sptlc3 and Enpp7 exhibited the largest transcriptional changes associated with the progression of untreated diabetes suggesting that changes in ceramide/sphingolipid metabolism to support the enlargement of the mucosal luminal interface." (PMID 34806320, 2021). "All except CRELD1 and ENPP7 have previously been directly or indirectly associated with T2DM, as well as other diabetes types." (PMID 37590326, 2023). "Overall, Sptlc3 and Enpp7 had the largest transcriptional changes and seem to support a proliferative effect of the mucosa during the advancement of diabetes." (PMID 34806320, 2021). "Taken together, ENPP7 appears to be understudied in general but may be relevant as a novel biomarker for diabetes." (PMID 37590326, 2023). "In addition, we identify several proteins biomarkers to be associated with glycaemic deterioration in diabetes, including NogoR (RTN4), IL-18Ra, CRELD1, ENPP7 and FAS." (PMID 37137910, 2023). "In contrast to ENPP7, we find that CRP, FAS, and GDF15 are the most studied targets for diabetes." (PMID 37590326, 2023).
dementia (1 paper, 2023). Loss of intellectual abilities interfering with an individual's social and occupational functions. "Seventeen proteins had more than a 50% difference between subjects with dementia and controls, including VIM (2.2 fold increase), NTproBNP (2.2 fold increase), CHIT1 (2.2 fold increase), NEFL (1.7 fold increase), ENPP7 (1.6 fold decrease), and FCGR2A (1.5 fold decrease)." (PMID 37175824, 2023).
serous ovarian cancer (1 paper, 2024). "However, it is worth noting that ACSM3 has demonstrated tumor-immunosuppressive properties in high-grade serous ovarian cancer, and ENPP7 activity has been relatively low in diseases with an increased risk of liver tumorigenesis." (PMID 38254162, 2024).
digestive system diseases (1 paper, 2024). "Especially, ENPP7 is almost only expressed in the duodenum and small intestine, so it is closely related to digestive system diseases." (PMID 39698091, 2024).
ENPP7 also shares sentences with these, for which no sentence is quoted: cancer (6 papers); colorectal cancer (5); tumor (5); ulcerative colitis (3); Familial adenomatous polyposis (2); gallstones (2); hepatocellular carcinoma (2); inflammatory bowel disease (2); liver cancer (2); liver diseases (2); primary sclerosing cholangitis (2); adenocarcinoma (1); adenoma (1); cholangiocarcinoma (1); cholangitis (1); cholestasis (1); Cholestatic liver disease (1); colon adenoma (1); colorectal adenocarcinoma (1); Klatskin tumour (1); necrotizing enterocolitis (1); pancreatic cancer (1); pancreatitis (1); steatosis (1).